VAMP8 (vesicle associated membrane protein 8)
Diseases named in the same sentence as VAMP8 in open-access papers (continued):
Sharing a sentence is not in itself a finding about the gene and the disease.
insulinoma (1 paper, 2022). "Native SNARE complexes from insulinoma INS8332/13 lysates were isolated by incubation with anti-VAMP2 or VAMP8 antibody-coated superparamagnetic beads followed by extensive washing, then purified α-SNAP and NSF added in presence of ATP-Mg2+ or EDTA." (PMID 36316316, 2022).
ischemia (1 paper, 2024). A hypoperfusion of the BLOOD through an organ or tissue caused by a PATHOLOGIC CONSTRICTION or obstruction of its BLOOD VESSELS, or an absence of BLOOD CIRCULATION. "We first investigated the correlation variations between NSF activity and the expressions of STX17 and VAMP8 after the ischemia." (PMID 39155286, 2024). "The relevant alterations between NSF activity and expressions of STX17 and VAMP8 were investigated after ischemia." (PMID 39155286, 2024).
ischemic stroke (1 paper, 2024). A stroke disorder caused by obstruction of blood flow to the brain, due to thrombotic (local blood clot formation) or embolic (due to a blood clot or other material traveling from another site) event. "The results demonstrated that NSF was prominently inhibited, coupling with decreased expressions of STX17 and VAMP8 in penumbral neurons 48 h after ischemic stroke, as well as in HT22 neurons 2 h after OGD." (PMID 39155286, 2024).
kidney stones (1 paper, 2024). "Notably, genes PPP2R3A for BUN, VAMP8 for UACR, DOCK7 for creatinine, and HIBADH for kidney stones were identified as shared risk genes by all three methods." (PMID 39086896, 2024).
leukemia (1 paper, 2022). A malignant (clonal) hematologic disorder, involving hematopoietic stem cells and characterized by the presence of primitive or atypical myeloid or lymphoid cells in the bone marrow and the blood. "Our previous study indicated that Rab44 protein associates with vesicle-associated membrane protein 8 (VAMP8), a v-SNARE protein, in native mouse bone marrow mast cells as well as ectopic expression cells of rat basophilic leukemia-2H3." (PMID 35743062, 2022).
lung carcinoma (1 paper, 2023). "For instance, VAMP8 inhibited lung cancer metastasis through the RAB37-mediated exocytosis of anti-metastasis cargos." (PMID 37405957, 2023).
neuroblastoma (1 paper, 2022). Neuroblastoma (NB) is the most common solid, extracranial childhood tumor. "We previously showed that VAMP8 overexpression increased Tau secretion in the neuroblastoma cell line N2a, which was correlated to a decrease of intracellular Tau." (PMID 36313558, 2022).
rhinitis (1 paper, 2025). An inflammation of the mucous membrane lining the nose, usually associated with nasal discharge. "Comparative analysis also revealed higher VAMP8 expression in NPC samples compared with rhinitis controls, and its upregulation was associated with poorer prognosis in NPC." (PMID 39854120, 2025).
sarcoma (1 paper, 2023). A usually aggressive malignant neoplasm of the soft tissue or bone. "We thus instead examined the VAMP8 expression from sarcoma cohorts in The Cancer Genome Atlas (TCGA) database and observed the significant downregulation of VAMP8 in metastatic sarcoma." (PMID 37405957, 2023). "The analysis revealed a downregulation of VAMP8 mRNA in sarcoma cells." (PMID 37405957, 2023).
Splenomegaly (1 paper, 2019). Abnormal increased size of the spleen. "Colon length, thickness, and splenomegaly were not significantly different between Vamp8−/− and Vamp8+/+ littermates." (PMID 31541089, 2019).
Stroke (1 paper, 2012). Sudden impairment of blood flow to a part of the brain due to occlusion or rupture of an artery to the brain. "A number of new stroke-genes related to T- and dendritic cell activation and differentiation including Cd 8a, Tmem176b, Unc93b1, Vamp8, and Wipf1 also displayed persistent upregulation." (PMID 23251410, 2012).
tumor (16 papers, 2009 to 2026). "ERRα inhibition impaired the transcriptional expression of LAMP2 and VAMP8 and blocked the fusion of autophagosomes with lysosomes, causing the impairment of the autophagy-lysosome pathway and tumor repression in RCC." (PMID 39820331, 2025). "In conclusion, our study uncovers a novel tumor-suppressive role of VAMP8 in OS and provides insights into the underlying molecular mechanisms." (PMID 37405957, 2023). "Mice in the VAMP8 knockdown group exhibited significantly slower tumor growth rates and reduced tumor weights compared to the control groups." (PMID 39854120, 2025). "Taken together, our findings unraveled a novel tumor suppressor function of VAMP8 in OS and provide insights into potential molecular mechanisms involved." (PMID 37405957, 2023). "For example, Vamp8 levels were low in the majority of the highly aggressive ER-negative subtype, whereas a minority of ER-positive tumours had high Vamp8 levels." (PMID 28062852, 2017). "There was a highly significant inverse correlation between membranous Vamp8 staining and tumour grade." (PMID 28062852, 2017). "We, therefore, looked at the distribution of Vamp8 in a number of tumours from MMTV-PyMT mice and compared this with their histopathology." (PMID 28062852, 2017). "In addition, the cancer stemness score (RNAss) was negatively correlated with LAIR1 and VAMP8 and positively correlated with CKAP2L and SOX6, indicating that these hub genes are linked to tumor stemness-related characteristics." (PMID 41614933, 2026). "The results showed a decreased intensity of LAMP2 and VAMP8 in cells and tumor tissues of shERRα." (PMID 39820331, 2025). "Thus, Rab17 and Vamp8-dependent sequestration of NRP2 within the endosomes of tumour cells is likely to represent a remnant of the transcytotic system that still acts to suppress basement membrane disruption and the DCIS to IDC transition." (PMID 28062852, 2017). "Importantly, VAMP8 overexpression counteracts the tumor‐suppressive effects of miR‐185." (PMID 39854120, 2025). "Moreover, dephosphorylation of VAMP8 could be responsible for tumor malignancy, and VAMP8 phosphorylation could play an important role on regulating cancer cell survival." (PMID 34645799, 2021). "IHC results confirmed that inhibition of ERRα acetylation repressed the expression of Ki67 in tumor tissues, the expression of LAMP2 and VAMP8 were also inhibited by XCT-790 and CBP-30." (PMID 39820331, 2025). "Functional assays demonstrate that VAMP8 exerts a tumorigenic role in NPC, enhancing cell proliferation, migration, and tumor growth." (PMID 39854120, 2025). "We found that Vamp8 levels were high in the less-advanced MMTV-PyMT tumours that displayed DCIS-like pathology, whereas in more invasive tumours with IDC-like characteristics, Vamp8 levels were low." (PMID 28062852, 2017). "We focused in those genes that were significantly differently methylated in the basal-like tumor subtype (HOXA9, SOX1, VAMP8, and TNFRS10D) and those that were significantly hypermethylated in the luminal B tumors (NPY, RASSF1, HS3ST2, DBC1, FGF2, CD40." (PMID 20920229, 2010). "We hypothesize that the expression patterns of QRICH1 and VAMP8 contribute to defining the trajectory trail for MSig GBM subtypes, offering insights into the tumour's evolutionary driving forces." (PMID 41292185, 2025). "Indeed, the majority of low-grade (grade I) tumours had high levels of Vamp8, whereas most high-grade (grade III) tumours displayed less-intense membranous Vamp8 staining." (PMID 28062852, 2017).
infection (15 papers, 2014 to 2026). The state of being infected such as from the introduction of a foreign agent such as serum, vaccine, antigenic substance or organism. "VAMP7 and Vti1B were localized to the PVM within 30 min post-infection, suggesting potential roles during invasion, while VAMP8 and Stx7 appeared later around 24 h post infection (hpi), coinciding with increased nutrient acquisition." (PMID 41972675, 2026). "infection exacerbates the pathogenesis of MI in the ischemic myocardium and VAMP8 plays a critical role in this process." (PMID 37723152, 2023). "infection, low incidences of cardiac rupture and cardiomyocyte hypertrophy were observed, and autophagy was activated in VAMP8-K47A mice." (PMID 37723152, 2023). "Citrobacter shedding in stool samples at the peak of infection was also significantly higher in Vamp8−/− as compared to Vamp8+/+ littermates." (PMID 31541089, 2019). "To validate these finding in vivo, we performed colonic loop infections with E. histolytica in Vamp8−/− and Vamp+/+ littermate controls." (PMID 28974617, 2017). "The vesicle SNARE VAMP8 on mucin granules within goblet cells is specifically activated following infection with the protozoan parasite Entamoeba histolytica that is known to induce potent hyper-secretion and coordinates mucin exocytosis." (PMID 29234672, 2017). "Vamp8−/− animals displayed TUNEL+ apoptotic cells at the apical surface of the epithelium following infection with E. histolytica (white arrows); however, Vamp8+/+-infected littermates did not." (PMID 28974617, 2017). "infection in vivo leads to the cleavage of VAMP8 and suppression of autophagy; and P.g." (PMID 37723152, 2023). "The Vamp8 protein, enriched in the indirect infection of 24 h, is a well-studied SNARE protein." (PMID 33946162, 2021). "Additionally, at day 14 Vamp8+/+ largely cleared the infection, whereas in Vamp8−/−Citrobacter persisted localizing throughout the entire GI tract including the small intestine." (PMID 31541089, 2019). "This may be related to the fact that Leishmania promastigotes can efficiently target VAMP8 during the infection process." (PMID 27280768, 2016). "induces phagocytotic entry into the host cells by using VAMP8 at the entry site; recruits VAMP2, VAMP3, and VAMP4 on to the Salmonella-containing vacuoles during infection; and uses VAMP7 for secretion of typhoid toxins outside the host cell." (PMID 39950824, 2025). "We discovered that 48 h post-infection, the expression levels of GNAS, PRKACA, RAP1A, and VAMP8 were all dramatically downregulated, which inhibited Rap1 activation and transactivation." (PMID 37211158, 2023). "Similarly, VAMP8-mediated mucin exocytosis is equally important during infection with E. histolytica, as mice lacking Vamp8 have increased apoptosis and cytolysis of epithelial cells due to aberrant mucin release." (PMID 29234672, 2017).
cancer (13 papers, 2011 to 2026). A tumor composed of atypical neoplastic, often pleomorphic cells that invade other tissues. "Subsequently, we performed a series of experiments to study the role of VAMP8 in cancer cell migration and invasion." (PMID 37405957, 2023). "To investigate the function of VAMP8 in OS, we initially analyzed the transcript levels of VAMP8 in Cancer Cell Line Encyclopedia (CCLE) database." (PMID 37405957, 2023). "Overexpression of VAMP8 inhibited cancer cell migration and invasion, and low expression of VAMP8 promoted the progression of OS." (PMID 37405957, 2023). "Recent studies have revealed the significance of VAMP8 in regulating various signaling pathways in various types of cancer." (PMID 37405957, 2023). "Given the significant downregulation of VAMP8 in OS and its clinical relevance, we investigated whether VAMP8 plays a role in regulating the cancer progression." (PMID 37405957, 2023). "Considering what was yet unknown in the current literature on cancer cell metabolism we investigated two genes whose expression was HER2 oncogene-regulated, VAMP8 and PHGDH, for their roles in HER2 oncogene-driven insulin-independence." (PMID 21437235, 2011). "VAMP8 is involved in calcium-dependent exocytosis process and SEC14L1 is a membrane trafficking protein, and none of them is linked to cancer pathways." (PMID 21909426, 2011). "With this procedure, we recorded about 100 STED platelet images each, for six different proteins (VAMP7, VAMP8, STX11, SNAP23, TSP1, and VEGF) and for five different categories of platelets; incubated with cancer cells (MCF-7, MDA-MD-231, EFO-21), non-cancer cells (MCF-10A), or no cells at all (R)." (PMID 35729633, 2022).
bacterial infection (3 papers, 2023 to 2025). "Moreover, the increased expressions of both CTSB and VAMP8 are associated with inflammatory and bacterial infection processes, which may indirectly reflect the dysbiosis of pulmonary immunity and microbiota triggered by ammonia exposure." (PMID 37250049, 2023).
kidney disease (1 paper, 2018). "Intriguingly, G1 and G2 variants of apoL1, which are associated with increased kidney disease risk in humans, interact with and impair VAMP8 function in human cells leading to changes in autophagosome-lysosome fusion dynamics that may underlie the observed kidney pathology." (PMID 29346416, 2018).
VAMP8 also shares sentences with these, for which no sentence is quoted: ovarian carcinoma (2 papers); type 2 diabetes (2); acute respiratory distress syndrome (1); breast (1); bronchopulmonary dysplasia (1); cardiovascular diseases (1); chronic GVHD (1); coronary artery disease (1); dry eye (1); hydronephrosis (1); Hypertension (1); Intellectual disability (1); invasive carcinoma (1); migraine (1); pancreatic cancer (1); pancreatic ductal adenocarcinoma (1); parasite infection (1); Parkinson disease (1); prostate carcinoma (1); renal tumours (1); type 2 diabetes mellitus (1); viral diseases (1).